COL11A1 (collagen type XI alpha 1 chain)
Diseases named in the same sentence as COL11A1 in open-access papers (continued):
Sharing a sentence is not in itself a finding about the gene and the disease.
cancer (continued). "The ITGA11+/ COL11A1+ CAFs subtype, therefore, may serve as a key determinant for the progression of NSCLC and may be considered for novel anti‐tumor strategies through the blockade of cancer cell–stroma interactions." (PMID 33682233, 2021). "Interestingly, in normal skin, COL11A1 expression is low or absent, but in some types of cancer, COL11A1 is highly expressed." (PMID 31216669, 2019). "We therefore presume that neither the COL11A1 signature nor our 151-gene probe set prognostic signature is solely attributable to CAFs, but may in fact be expressed by cancer cells." (PMID 27028324, 2016). "However, no significant prognostic value of COL11A1 was observed in other cancer types." (PMID 35892083, 2022). "In addition, it is not clear whether the COL11A1, secreted by cancer cells and CAFs, is structurally and functionally similar." (PMID 33668097, 2021). "Interestingly, this group did not see ERK activation by COL11A1 in this cell line, suggesting that COL11A1 may activate different signaling programs depending on the cancer type." (PMID 33668097, 2021). "In both of these examples, these gene lists are clearly due to the presence of the COL11A1/INHBA/THBS2-expressing CAFs and therefore these are not cancer-type specific subtype signatures." (PMID 34283835, 2021). "The CD24+/CD44+ cells with high COL11A1 expression may undergo EMT.COL11A1 is absent in normal pancreatic tissues, which may be a crucial factor for distinguishing between cancer initiation and development." (PMID 35327583, 2022).
tumor (159 papers, 2012 to 2026). "Taken together, these results suggest that COL11A1 is associated with tumor cell invasion and migration and, thus, inhibiting its expression can suppress invasion and migration in HepG2 cells." (PMID 39857819, 2025). "Considering the significant impact of COL11A1 mutations on immune pathways, we compared the effects of COL11A1 mutations on tumor immune infiltration across various tumor types." (PMID 40322427, 2025). "Collagen proteins (COL1A1, COL1A2, COL3A1, COL11A1) were associated with tumor progression and metastasis." (PMID 40867231, 2025). "The top 20 targets highly upregulated in tumor compared to all NT (ranked according to the log2(FC) T vs CT) include transcripts encoding for COL11A1, TNC, PTK7, and P4HA3." (PMID 39681068, 2024). "COL11A1 is also associated with tumor aggressiveness and poor clinical outcomes via the TGF/β1/MMP3 axis." (PMID 35681617, 2022). "High COL11A1 levels are associated with tumor aggressiveness, chemoresistance, and poor survival in various solid tumor types." (PMID 34944877, 2021). "COL11A1 can also be used as a biomarker to identify patients who have a high risk of developing chemoresistance and tumor recurrence." (PMID 33668097, 2021). "COL11A1 expression has been detected in not only tumor cells, but also other tumor-associated stromal cells." (PMID 33668097, 2021). "High levels of COL11A1 are often associated with aggressive tumor phenotype and poor prognosis in multiple solid tumors types such as ovarian, breast, pancreas, and colorectal cancer." (PMID 33668097, 2021). "A microarray-based study reveals that the COL11A1 gene is associated with the disease progression and poor survival in ovarian cancer and regulates cell invasiveness required for tumor formation." (PMID 33597969, 2021). "The observation that LY treatment is associated with reduced expression of VCAN and COL11A1 in tumor stroma provides evidence of a potential TGF-β-dependent mechanism of growth inhibition." (PMID 30087253, 2018). "Of the 9 genes tested, 8 (THBS1, CYR61, CTGF, MXRA5, SPP1, LTBP2, TGFBR1 and COL11A1) were found by qRT-PCR to be significantly differentially expressed in tumor-associated fibroblasts, for a validation rate of 89%." (PMID 26575166, 2015). "In tumours, the expression of the COL11A1 gene is currently associated to a fibroblast-like stromal phenotype but the origin and nature of the cells which produce procollagen and collagen 11A1 remain controversial to some extent." (PMID 25417197, 2014). "Further enrichment analysis suggested that COL11A1 mutations may alter the tumor immune microenvironment by affecting immune-related pathways, such as leukocyte activation and chemokine signaling." (PMID 40322427, 2025). "Immuno-infiltration analysis also revealed that COL11A1 mutations might alter the tumor microenvironment by influencing immune cell infiltration." (PMID 40322427, 2025). "Moreover, recent studies have highlighted that in lung cancer patients who are non-responders to treatment, there is an increased proportion of COL11A1+ tumor-associated fibroblasts (CAFs) that interact with tumor cells via the DDR1-collagen axis." (PMID 40713963, 2025). "In addition, due to the lack of functional experimental verification, the specific effects of COL11A1 mutation on the tumor immune microenvironment still need to be further explored." (PMID 40322427, 2025). "High COL11A1 levels are associated with tumor aggressiveness, chemoresistance, and a poor survival." (PMID 37386587, 2023). "Although it is mainly involved in the biological process of bone development, high levels of COL11A1 are associated with tumor metastasis, treatment resistance, and poor clinical outcome in several solid tumors types such as breast, pancreas, and colorectal cancers." (PMID 36389832, 2022). "COL11A1 expression has been detected in tumor cells as well as in tumor-associated stromal cells." (PMID 35847935, 2022).
tumor (continued). "Moreover, high TS COL11A1 staining in NB tumor samples was correlated with factors associated with poor prognosis and relapse." (PMID 36231134, 2022). "Altered expression of COL11A1/COL10A1 is associated with tumor development/progression." (PMID 27857161, 2016). "Additionally, collagen proteins (COL1A1, COL1A2, COL3A1, COL11A1) were linked to tumor progression and metastasis, while chaperonin-containing TCP1 (CCT) complex proteins and microtubule-associated proteins (TUBA1C, TUBB) were implicated in cytoskeletal organization and chemotherapy resistance." (PMID 40867231, 2025). "In conclusion, COL11A1 plays a pivotal role in shaping the tumor microenvironment by promoting fibroblast activation, stromal remodeling, and immune suppression." (PMID 41462920, 2025). "CAF-FAP showed higher expression of ECM fibrillar collagen COL11A1, which agreed with the dense and twisted fibers observed in the tumor stroma of FR‒ HCCs." (PMID 39870619, 2025). "This correlation is validated by the Kaplan–Meier survival curve, illustrating that patients with higher COL11A1 levels experience increased instances of metastasis, recurrence, or death compared to those with lower COL11A1 expression in the primary tumor." (PMID 39845732, 2025). "Studies have also demonstrated that COL11A1 expression differs between “immunologically hot” and “immunologically cold” tumor subtypes." (PMID 41462920, 2025). "The DEGs included genes involved in cell proliferation and migration (e.g., COL11A1), tumor‐promoting factors that degrade the extracellular matrix (e.g., MMP11), as well as immunosuppressive (TGFB1) and proinflammatory responses (TNFRSF6B, IFNGR2, GSDMB)." (PMID 40952312, 2025). "In CRC, the COL11A1 gene is excessively expressed and contributes to tumor advancement by upregulating other genes like THBS2, COL10A1, COL5A2, and COL1A2, thereby driving neoplasia." (PMID 40109582, 2025). "In conclusion, COL11A1 represents a promising direction in the search for novel biomarkers that integrate tumor biology, stromal remodeling, and immune interactions." (PMID 41462920, 2025). "Given the significantly higher expression of COL11A1 in tumor tissues, we further explored its influence on cell invasion and migration." (PMID 39857819, 2025). "We performed 48-h co-culture assays with COL11A1-positive pediatric tumor cell lines (OS: LM7, 143B; RMS: CCL-136, CRL-2061; EWS: A673) and COL11A1-negative primary fibroblasts." (PMID 38702309, 2024). "Intriguingly, both POSTN+ and PTGDS + CAFs were detected around the tumor islands, suggesting that these CAFs correspond to the mCAFs in our study as we used COL11A1 and PTGDS to localize them in the tissue." (PMID 39516494, 2024). "COL11A1-CAR T cells had significant anti-tumor activity as judged by bioluminescence imaging in 10/10 mice in comparison to NT T cells, which had no antitumor activity." (PMID 38702309, 2024). "Col11a1+ CAFs, which co-express LRRC15, are also associated with tumour progression in scRNA-seq and tissue-staining studies." (PMID 38791926, 2024). "COL11A1 is highly expressed in tumor-associated fibroblasts, which secrete COL11A1 into the ECM to regulate tumor cell proliferation, angiogenesis, invasion, and drug resistance." (PMID 38293522, 2024). "As they synthesize a range of ECM proteins including COL11A1, which we detected as dense fibers surrounding tumor nests, we propose that mCAFs play a crucial role in T cell marginalization." (PMID 39516494, 2024). "We observed CAR T cell expansion but limited persistence, and decreased expression of COL11A1 on day 65 post tumor cell injection, indicating that tumor recurrence is most likely due to both mechanisms." (PMID 38702309, 2024).
tumor (continued). "The results showed that the methylation level of COL11A1 in tumor tissues is significantly higher than that in normal tissues (p = 1.62e-12)." (PMID 38649961, 2024). "COL11A1+ fibroblasts can change the composition of the extracellular matrix and facilitate tumor invasiveness." (PMID 39716051, 2024). "In our study, we used TCGA + GTEx, GSE32863, and GSE75037 datasets to confirm that the expression of COL11A1 was significantly higher in tumor tissues than in normal tissues, which was verified by our own samples in IHC experiments." (PMID 38649961, 2024). "These authors explicitly described the role of COL4 and COL11A1 in matrix stiffness and tumor progression." (PMID 39769183, 2024). "Col11A1 is a key upregulated component of the Matrix Index, which predicts metastasis across many tumour types, including ovarian, pancreatic, and breast cancers." (PMID 38791926, 2024). "In the last few years, several works have reported COL11A1 as a tumor promoter in transitional bladder carcinoma relationships." (PMID 37760937, 2023). "Consistently, the expression of COL11A1 in various tumor tissues was significantly higher than adjacent normal tissues." (PMID 36744260, 2023). "For instance, excessive collagen type XI alpha 1 (COL11A1) secretion in OC is involved in enhancing cell invasiveness and tumor formation by activating matrix metalloproteinases (MMP)." (PMID 38264664, 2023). "This tumor location was selected to determine the clinical usefulness of COL11A1 in predicting invasiveness in borderline ovarian carcinomas, which pose serious difficulties in accurate diagnosis." (PMID 37760937, 2023). "Genes such as COL14A1, COL6A1, THBS2, COL4A2 and COL11A1 are involved in tumor migration and invasion." (PMID 37024829, 2023). "Recent evidence has shown that COL11A1 is frequently overexpressed in various tumors and its expression is highly correlated with tumor aggressiveness." (PMID 36835153, 2023). "In contrast, multiple genes were upregulated in tumour-associated myofibroblasts compared to their control counterparts, including SULF1, COL11A1 and LRRC15." (PMID 36720863, 2023). "The extracellular matrix (ECM) includes fibrillar collagens (e.g. COL1A1, COL5A2, COL11A1) as the major connective tissue components and tumor microenvironment." (PMID 36587397, 2023). "The results revealed that SPP1, COMP, THBS2, SERPINE1, and COL11A1 were highly expressed in tumor tissues, while MYH11, TAGLN, and CNN1 were lowly expressed." (PMID 36999888, 2023). "After this, there have been several publications that have described the overexpression of COL11A1 in tumor samples when compared with noninvasive samples or normal tissue." (PMID 37760937, 2023). "Strikingly, we discovered that while COL11A1 expression in the latter is nearly restricted to CAFsCOL11A1 in their vicinity, SOX10 + tumours produce COL11A1 in the tumour cells at varying rates." (PMID 34378164, 2022). "To test in an unbiased manner if COL11A1+ and COL11A1− tumor regions have distinct ECM patterns, we conducted computational image feature extraction and statistical analyses." (PMID 36497028, 2022). "Seven ECMGs (i.e. LAMB3, LAMA3, ITGB6, ITGB4, ITGA2, LAMC2, and COL11A1) were identified to be hub genes of PAAD, which were obviously up-regulated in PAAD and considerably linked to tumor stage as well as prognosis." (PMID 36311789, 2022). "Gene Ontology (GO) and Kyoto Encyclopedia of Gene and Genome (KEGG) all suggest that COL11A1 is related to tumor immunity." (PMID 36160004, 2022). "Further analysis of the patient's clinical information revealed higher COL11A1 expression in Stage IV and T4 stages than in other stages, and the expression elevated as tumor stage increased." (PMID 35669376, 2022). "Of note, COL11A1 expression by tumour cells was nearly exclusive to SGC that are derived from the intercalated duct or the acini." (PMID 34378164, 2022).
tumor (continued). "This nearly mutually exclusive pattern was sustained by the fact, that only 4% of all cases were positive for both tumour cell and stromal COL11A1, while 69% stained exclusively for either of the two patterns." (PMID 34378164, 2022). "To further assess the impact of COL11A1 on the tumor microenvironment, we evaluated the correlation between COL11A1 and immune infiltration using the GSVA package [version 1.34.0]." (PMID 36160004, 2022). "TGF-β3 induction by COL11A1 reinforced tumor–fibroblast crosstalk via heightened IL-6 production to stimulate the proliferation and invasion of tumor cells." (PMID 35847935, 2022). "Further study found that the COL11A1 expression was significantly correlated with the degree of immune infiltration and the expression of a variety of immune cell markers in tumor tissue." (PMID 36160004, 2022). "In this study, we noted that T cell-related markers, the main force in tumor immunity, were negatively correlated with COL11A1 expression." (PMID 36160004, 2022). "Co-culture of CAFs with SH-SY5Y NB cells enhanced tumor cell invasion, and CAF-associated COL11A1 expression was pivotal for the observed effect." (PMID 36231134, 2022). "We show that this feature of thin, linear collagen fibers in the presence of COL11A1 is preserved in the tumor microenvironment." (PMID 36497028, 2022). "Recently, we have discovered that in SGC, COL11A1 is not only expressed by CAFs but also by AdCy tumour cells." (PMID 34378164, 2022). "Of 149 up-regulated genes identified in tumor tissues, three ML algorithms identified COL11A1 as a hub gene." (PMID 36389832, 2022). "Collagen type XI tends to promote tumor progression, since the siRNA-knockdown of COL11A1 in ovarian and head and neck tumor cell lines significantly reduces cell invasion and proliferation." (PMID 36233024, 2022). "The results of the protein expression analysis suggested that COL11A1 had higher expression in tumor samples compared to normal tissues." (PMID 36389832, 2022). "In NSCLC, our group previously showed that COL11A1 was upregulated in tumor stroma compared with normal lung tissue and we further identified COL11A1 as one of the differentially expressed genes upregulated in CAFs vs. normal lung fibroblasts." (PMID 36233024, 2022). "We found that Snail acts as a fundamental factor in molecular transduction, by which COL11A1 manipulates tumor cell infiltration." (PMID 35327583, 2022). "If so, cells expressing mutant COL11A1 protein should be able to enhance neoplastic invasion by adjacent COL11A1 wild-type tumor cells when both contain oncogenic drivers." (PMID 34584216, 2021). "Consistent with previous clinical studies 24-26, we show that COL11A1 facilitates tumor progression in PDAC." (PMID 33531986, 2021). "Mutant COL11A1 enhanced invasion in both organoids and in vivo xenografts of human skin tissue and its targeted disruption blocked subcutaneous tumor growth as well." (PMID 34584216, 2021). "The gene signature upregulated by mutant COL11A1 therefore correlates with decreased survival across multiple tumor types." (PMID 34584216, 2021). "Previous studies suggested that COL11A1 regulates tumor progression through the APC/beta-catenin pathway, and inhibits apoptosis by modulating the NFkB pathway." (PMID 33428592, 2021). "The tumor-suppressive function of miR-335 is mediated by the suppression of COL11A1 expression, thereby reducing the invasive ability and chemoresistance of EOC cells via the Ets-1/MMP3 and Akt/c/EBPβ/PDK1 axes, respectively." (PMID 34944877, 2021). "Taken together, it is very likely that COL11A1 alters the mechanical properties of the ECM to increase tumor aggressiveness." (PMID 33668097, 2021). "Increasing evidence shows that COL11A1 promotes tumor cell aggressiveness through multiple mechanisms." (PMID 33668097, 2021). "Overall, human mesenchymal cells, tumor endothelial cells, and pancreatic stellate cells are the other cell types that show elevated COL11A1 expression." (PMID 33668097, 2021).